INS (insulin)
Diseases named in the same sentence as INS in open-access papers (continued):
Sharing a sentence is not in itself a finding about the gene and the disease.
colorectal neoplasm (4 papers, 2021 to 2025). A benign or malignant neoplasm that affects the colon or rectum. "Insulin has been implicated in colorectal tumor cell development; therefore, physical activity may reduce the risk of cancer by reducing insulin resistance and insulin levels, which impacts the insulin-like growth factor pathway." (PMID 34683079, 2021). "The androgenic influence on factors such as insulin resistance, chronic inflammation, and altered lipid metabolism may create a more permissive environment for colorectal tumor initiation and progression." (PMID 39980549, 2025). "Our results support the hypothesis that perturbations in insulin levels and glucose control partially contribute to the etiology of colorectal neoplasms." (PMID 34803930, 2021).
cutaneous melanoma (4 papers, 2014 to 2025). A primary melanoma arising from atypical melanocytes in the skin. "Consistently, insulin sensitivity (QUICKI) and BMI resulted positively associated with the diagnosis of cutaneous melanoma (p = 0.0001 and p = 0.0026, respectively)." (PMID 31749765, 2019).
dermopathy (4 papers, 2012 to 2026). "Furthermore, a significant association between insulin injection and proportion of dermopathy lesions was detected (P<0.05)." (PMID 27921026, 2016). "Another finding in this study was the significant association between diabetic dermopathy and insulin intake, which is in line with a study reporting a significantly lower incidence of dermopathy in the patients under treatment with insulin than those taking oral medications." (PMID 27921026, 2016).
Donohue syndrome (4 papers, 2020 to 2023). Leprechaunism is a congenital form of extreme insulin resistance (a group of syndromes that also includes Rabson-Mensenhall syndrome, type A insulin-resistance syndrome, and acquired type B insulin-resistance syndrome) characterized by intrauterine and mainly postnatal severe growth retardation. "The myotubes derived from individuals with Donohue syndrome exhibited defects in insulin signalling, glucose uptake and glycogen accumulation, as well as insulin-regulated gene expression." (PMID 32221645, 2020).
dwarfism (4 papers, 2012 to 2021). "Aging is also associated with an increase in bodyweight, fat mass and insulin resistance, and anti-aging interventions such as dietary restriction and dwarfism increase insulin sensitivity in mice." (PMID 34587168, 2021). "Male and female mice with a GH-insulin/IGF-I signaling deficiency exhibit dwarfism but also increased insulin sensitivity and the delayed manifestation of fatal malignancies and increased health and lifespan." (PMID 31728501, 2019). "As has been shown in multiple studies of dwarfism, mice with reduced levels of GH and IGF1 are insulin sensitive." (PMID 23077600, 2012). "The long-lived GH-resistant GH receptor (GHR)-KO mice which have high GH level, as well as Ames dwarf and Snell dwarf mice lacking GHexhibit dwarfism, increased subcutaneous adiposity, change in tissue sizes, and increased insulin sensitivity." (PMID 25239873, 2014).
dysautonomia (4 papers, 2005 to 2025). An acute or chronic disorder, affecting the sympathetic or parasympathetic nervous system. "The supposed mechanism may be the dysautonomia in PD which leads to beta cells dysfunction and insufficient insulin concentrations in response to the elevated PG levels." (PMID 34804608, 2021). "Thus, dysautonomia in PD may lead to beta cells dysfunction and insufficient insulin concentrations in response to the elevated PG levels." (PMID 34804608, 2021).
eczema (4 papers, 2008 to 2022). "Predisposing factors include trauma, surgery, burns and eczema, less commonly associated factors includes insect bites and subcutaneous insulin injection, an association between the use of non-steroidal anti-inflammatory and NF has been reported." (PMID 18842146, 2008). "Indeed, topical steroids are often used for long-term control of eczema despite contraindications, and this could not only worsen eczema, but also elicit insulin resistance." (PMID 28716044, 2017). "Anti-hypertensive agents were given for HPT, oral hypoglycemic agents with or without insulin for DM, inhaled salbutamols with or without inhaled corticosteroids for bronchial asthma and topical steroids cream for eczema." (PMID 36432649, 2022).
Fever (4 papers, 2015 to 2026). Body temperature elevated above the normal range. "Hyperthermia (HT) and passive heat therapy (hT) activate protective stress responses through HSP induction, mimicking some benefits of exercise and improving glycemic control, insulin sensitivity, and vascular health." (PMID 41777867, 2026).
fracture (4 papers, 2014 to 2024). "Fully adjusted Cox regression models found an increased fracture risk in women treated with insulin, compared with controls, for any fracture (HR, 1.71; 95% CI, 1.16-2.54) and MOF (HR, 1.89; 95% CI, 1.24-2.87) but not for hip fracture (HR, 1.14; 95% CI, 0.42-3.08)." (PMID 39106069, 2024).
gall bladder cancer (4 papers, 2008 to 2025). "Using GLP-1 RA or metformin vs. insulin, can reduce CRC and gall bladder cancer risk." (PMID 40563926, 2025). "Observational study reveals that insulin is associated with an increased risk of extrahepatic cholangiocarcinoma (ECC), but not intrahepatic cholangiocarcinoma (ICC) or gallbladder cancer (GBC)." (PMID 35933633, 2022).
gastritis (4 papers, 2014 to 2019). Inflammation of the stomach. "The other one; H. pylori-induced gastritis can potentially affect the secretion of gastric hormones, including leptin, ghrelin, gastrin, and somatostatin, which could affect insulin sensitivity and glucose homeostasis." (PMID 27148410, 2016).
Genetic obesity (4 papers, 2017 to 2020). "In summary, this study shows that BPL1 probiotic supplementation improves abdominal adiposity, insulin sensitivity, and some mental health symptoms in children and adolescents with genetic obesity." (PMID 33066107, 2020).
glucocorticoid deficiency (4 papers, 2012 to 2018). "Hypoglycemic attacks are considered to be caused by enhanced insulin sensitivity secondary to glucocorticoid deficiency." (PMID 22839422, 2012). "However, hypoglycaemia may occur in association with primary and secondary glucocorticoid deficiency as a result of an enhanced insulin sensitivity." (PMID 25214204, 2014).
gynecologic cancer (4 papers, 2015 to 2025). "Treatment strategies for managing metabolic dysregulation in patients with gynecological cancers include weight management, statin therapy, and insulin-sensitizing medications." (PMID 38768058, 2024). "For example, some low-calorie sweeteners have been shown to alter insulin sensitivity and estrogen signaling, which could theoretically influence gynecologic cancer development." (PMID 40988757, 2025). "Similar to other cancers, gynecologic cancers have several common mechanisms with T2DM, including increased insulin and IGF signaling and chronic inflammation." (PMID 25866823, 2015).
hyperprolactinaemia (4 papers, 2021 to 2025). "In turn, oral contraceptives worsened insulin sensitivity and increased triglycerides, hsCRP, fibrinogen and UACR, already impaired by the presence of prolactin excess." (PMID 37176648, 2023).
Hypoglycemic encephalopathy (4 papers, 2025). Brain damage related to a lowering of blood glucose below a critical level (around 30 mg/dl), which may lead to confusion, lethargy and delirium followed by seizures and coma. "The related products of the tryptophan metabolism pathway have a certain diagnostic value for hypoglycemic encephalopathy and forensic identification of insulin overdose-induced hypoglycemic encephalopathy death." (PMID 40362391, 2025). "The results indicated an overall upward trend in the tryptophan metabolism pathway in patients with hypoglycemic encephalopathy and rats with hypoglycemic encephalopathy caused by insulin overdose, while serum glutamate levels declined." (PMID 40362391, 2025). "Investigating metabolic alterations in hypoglycemic encephalopathy provides evidence supporting clinical diagnosis and treatment while also offering valuable forensic insights into cases related to insulin overdose fatalities." (PMID 40362391, 2025). "This study combined MR analysis of serum metabolites in hypoglycemic encephalopathy (HE) patients with untargeted metabolomics profiling in insulin overdose-induced HE rat models." (PMID 40362391, 2025). "Based on these findings, this study was conducted to investigate insulin-induced hypoglycemic encephalopathy." (PMID 40362391, 2025). "For elderly diabetic patients, close monitoring is essential, and insulin or oral hypoglycemic doses should be adjusted promptly if they have infections or reduced food intake to prevent metabolic/hypoglycemic encephalopathy." (PMID 40385584, 2025). "Additionally, metabolomics methods were utilized to detect differential metabolites in the serum of a rat model of hypoglycemic encephalopathy induced by insulin overdose." (PMID 40362391, 2025).
Ketonuria (4 papers, 2005 to 2023). High levels of ketone bodies (acetoacetic acid, beta-hydroxybutyric acid, and acetone) in the urine. "In the present study, the levels of insulin, HOMA-IR, FPG, and TG were significantly lower in the ketonuria group than in the nonketonuria group." (PMID 34684404, 2021). "Compared to the nonketonuria group, the ketonuria group was younger (41.1 ± 10.0 vs. 44.6 ± 11.2 years, p < 0.001), had lower levels of FPG (87.2 ± 9.1 vs. 91.0 ± 8.1 mg/dL, p < 0.001), insulin (4.1± 2.3 vs. 6.2 ± 3.7 microU/mL, p < 0.001), and HOMA-IR (1.0 ± 0.5 vs. 1.5 ± 0.9, p < 0.001)." (PMID 34684404, 2021).
latent autoimmune diabetes in adults (4 papers, 2019 to 2025). Latent autoimmune diabetes in adults (LADA) is a form of diabetes mellitus type 1 that occurs in adulthood, often with a slower course of onset than type 1 diabetes diagnosed in juveniles. "Latent autoimmune diabetes in adults (LADA) is one of the adult-onset autoimmune diabetes, characterized by autoimmune destruction of pancreatic beta cells, leading to deficient insulin secretion." (PMID 40226121, 2025).
Leprechaunism (4 papers, 2013 to 2022). "Notably, an IR D707A mutation has been found in patients with leprechaunism, a rare genetic disease with severe insulin signaling defects." (PMID 31436533, 2019).
narcolepsy (4 papers, 2018 to 2022). A sleep disorder characterized by a tendency for excessive sleepiness during the day which occurs even after adequate sleep in the nighttime. "The greater proportion of fat oxidation and lower carbohydrate consumption may imply a state of insulin resistance, which is typical of the metabolic system of patients with narcolepsy, even at an early age." (PMID 36422261, 2022). "Interestingly, after adjusting for BMI, patients with narcolepsy remained significantly higher in waist circumference, lower in HDL, and higher in glucose/insulin ratio compared with controls." (PMID 36422261, 2022).
Neonatal sepsis (4 papers, 2015 to 2025). Systemic inflammatory response to infection in newborn babies. "10% neonates in insulin alone group developed neonatal sepsis as compared to 3.3% in metformin plus insulin group, P = 0.094." (PMID 25874236, 2015).
oral cancer (4 papers, 2012 to 2026). "Altered insulin sensitivity and lipotoxicity are mechanisms that may link membrane fluidity to oral cancer risk." (PMID 36209108, 2022).
ovarian hyperstimulation syndrome (4 papers, 2014 to 2025). A complication of ovulation induction in infertility treatment. "Furthermore, insulin can stimulate VEGF secretion while high levels of VEGF have been associated with occurrence and severity of ovarian hyperstimulation syndrome (OHSS) in women with PCOS and negative conception rates augmenting its role in PCOS pathophysiology." (PMID 31737638, 2019).
paraganglioma (4 papers, 2019 to 2023). A benign or malignant neoplasm arising from paraganglia located along the sympathetic or parasympathetic nerves. "Hypoglycemia has also been reported in paragangliomas, and co-secretion of insulin and catecholamines may rarely occur." (PMID 31275775, 2019).
paraplegia (4 papers, 2017 to 2025). Complete paralysis of the lower half of the body including both legs, often caused by damage to the spinal cord. "In a large study on glucose metabolism, individuals with tetraplegia had poorer glucose and insulin profiles than paraplegia (after oral glucose tolerance test)." (PMID 34417550, 2021). "While just 6 weeks of MICT can also enhance fasting markers of hepatic insulin sensitivity in persons with paraplegia, the effects on postprandial markers of peripheral insulin sensitivity are negligible." (PMID 31409383, 2019). "Six weeks of home-based moderate-intensity arm-crank exercise in inactive persons with chronic paraplegia significantly improved (i) functional capacity (V ̇O2peak and power output), (ii) fasting insulin concentrations, and (iii) HOMA-IR compared with the CON." (PMID 28753161, 2017). "BMI seemed to affect the disparity of insulin between individuals with tetraplegia and paraplegia." (PMID 34417550, 2021). "The mean serum insulin levels in individuals with tetraplegia were 9.8 uU/mL ± 5.4 compared to those with paraplegia 8.9 uU/mL ± 4.2, and the pooled difference between the groups was not statistically significant (WMD −0.3, 95% CI −1.8, 1.1, p < 0.001, I2 81.6%)." (PMID 34417550, 2021). "Tetraplegia was associated with greater visceral fat, poorer glycemic control, and lower BMI, insulin sensitivity, high-density lipoprotein-cholesterol (HDL-C), and triglycerides than paraplegia." (PMID 40363903, 2025).
Pituitary (4 papers, 2020 to 2025). "This preclinical study shows that a dietary intervention that results in lower serum insulin levels leads to lower insulin signals within the neuroendocrine cells and has a striking suppressive effect on the development and progression of both pancreatic and pituitary NETs." (PMID 37679316, 2023).
pituitary adenomas (4 papers, 2008 to 2023). "Therefore, in patients with PRL-secreting pituitary adenomas control of PRL excess by dopamine agonists is mandatory to improve glucose and insulin abnormalities." (PMID 31191454, 2019).
polycystic kidney disease (4 papers, 2015 to 2024). A usually autosomal dominant and less frequently autosomal recessive genetic disorder characterized by the presence of numerous cysts in the kidneys leading to end-stage renal failure. "The transcription factor Gli-similar 3 (Glis3) plays a critical role in the generation of pancreatic ß cells and the regulation insulin gene transcription and has been implicated in the development of several pathologies, including type 1 and 2 diabetes and polycystic kidney disease." (PMID 26147758, 2015).
Prader-Willi syndrome (4 papers, 2013 to 2024). "It has been suggested that patients with Prader-Willi syndrome have central adrenal insufficiency under stressful conditions, delayed peak response of cortisol to insulin challenge, and small-sized adrenal glands in autopsies." (PMID 39423809, 2024). "To investigate pancreatic islet beta-cell dysfunction in Prader-Willi syndrome (PWS), we engineered 3-megabase multigene deletions of the PWS imprinted domain in the INS-1 insulin-secreting cell line." (PMID 37068109, 2023). "In Prader-Willi syndrome ghrelin is elevated to levels not explained by relative insulin sensitivity and lower insulin levels." (PMID 24555152, 2013).
premature ovarian failure (4 papers, 2019 to 2023). "When compared with an age, sex, and BMI-matched cohort of women with primary ovarian failure (thus removing estrogen deficiency as a confounder), the TS group had higher rates of glucose abnormalities and demonstrated impaired insulin secretion." (PMID 36875465, 2023). "For example, the ovary-specific deletion of Pten or Pdk1 causes premature ovarian failure despite opposite regulatory roles in the insulin signaling pathway, implying the complexity of the mechanism." (PMID 31009498, 2019). "Inhibiting the PI3K/AKT pathway in the insulin signaling pathway can accelerate granulosa cell (GC) apoptosis and result in premature ovarian failure." (PMID 38057756, 2023).
progeria (4 papers, 2020 to 2023). "Mechanistically, genetic studies have pointed to the involvement of several key events, notably DNA damage, particularly in the progeria/progeroid syndromes and activities of the insulin/IGF1/mTOR/FOXO pathway in longevity." (PMID 35531366, 2022). "In this study, energy metabolism, glucose metabolism, beta-cell function and insulin sensitivity were studied in Ercc1d/− mice, which model a human progeroid syndrome." (PMID 33493548, 2021). "On the other hand, insulin phosphorylated Akt2 in WM and LMN, but failed to do so in LM cells, implicating Akt2 signaling in the insulin resistance of progeria myoblasts." (PMID 36797255, 2023).
Respiratory distress (4 papers, 2017 to 2025). Respiratory distress is objectively observable as the physical or emotional consequences from the experience of dyspnea. "Data from our study clearly suggest an increased risk of neonatal respiratory distress in the insulin-treated GDM group, and this risk was also increased for deliveries after 37 weeks." (PMID 28197657, 2017). "The excess risk of cardiac malformations and respiratory distress observed in the GDM group was also due to the insulin-treated GDM group." (PMID 28197657, 2017). "In this restricted GDM group, the risk of respiratory distress among deliveries after 28 weeks and the risk of perinatal death among deliveries after 37 weeks in the insulin-treated group were no longer significantly increased (OR 1.0 [95% CI 0.9, 1.1] and OR 0.9 [95% CI 0.6, 1.5], respectively)." (PMID 28197657, 2017).
retinal ischemia (4 papers, 2019 to 2025). A ischemic disease that involves the retina. "PGZ has shown protective effects for retinal ischemia/reperfusion injury, optic nerve crush injury, and normalized insulin signaling in diabetic rat retinas." (PMID 36613856, 2022). "Improved insulin sensitivity may reduce retinal ischemia, oxidative stress, and inflammation, thereby preserving vascular integrity and reducing DR susceptibility." (PMID 40778361, 2025).
retinopathy of prematurity (4 papers, 2016 to 2023). A bilateral retinopathy characterized by neovascularization, scarring, retinal detachment, and eventually blindness. "RNA binding motif protein 39 (RBM39) were associated with a higher risk of insulin in clinically significant retinopathy of prematurity." (PMID 34084770, 2021).
rhabdomyosarcoma (4 papers, 2014 to 2016). A rare aggressive malignant mesenchymal neoplasm arising from skeletal muscle. "On the other hand, insulin activates the transcriptional activity of HNF4 via forkhead in human rhabdomyosarcoma (FKHR) as a signal-regulated transcriptional inhibitor." (PMID 25264921, 2014). "Furthermore, in RC13 rhabdomyosarcoma cells and L6 myocytes, insulin regulates Pi uptake upstream of Akt, which involves activation of PI3K and PDK1." (PMID 27338702, 2016).
SARS-CoV infection (4 papers, 2020 to 2022). "SARS-CoV infection, for example, was linked to an increase in the demand for high doses of insulin in insulin-dependent individuals (approaching or above 100 IU/day)." (PMID 35711466, 2022).
spinal cord injury (4 papers, 2009 to 2025). Penetrating and non-penetrating injuries to the spinal cord resulting from traumatic external forces (e.g., WOUNDS, GUNSHOT; WHIPLASH INJURIES; etc.). "Our goal is to determine if low force electrically induced exercise (LFE) will modulate the post prandial insulin and glucose response in people with and without spinal cord injury (SCI)." (PMID 36278750, 2022).